SNORD114-4 (small nucleolar RNA, C/D box 114-4)
Synonyms: 14q(II-4)
Gene: Small nucleolar RNA gene on chromosome 14 (100,954,374 to 100,954,448, forward strand). Ensembl gene ENSG00000200832.
Gene Ontology:
Biological process: RNA processing
Cellular component: nucleolus
Homologues: Orthologues: chimpanzee SNORD114-4 (97% identical), macaque SNORD114-4 (96% identical). Paralogues in human: SNORD114-17 (79% identical), SNORD114-14 (77% identical), SNORD114-13 (76% identical), SNORD114-3 (76% identical), SNORD114-31 (76% identical), SNORD114-12 (75% identical), SNORD114-11 (73% identical), SNORD114-21 (72% identical), SNORD114-1 (71% identical), SNORD114-15 (71% identical), SNORD114-19 (71% identical), SNORD114-23 (71% identical), and 26 more.